ENSG00000267952 (novel transcript)
Gene: Protein-coding gene on chromosome 19 (7,507,052 to 7,519,622, forward strand). Ensembl gene ENSG00000267952.
Genetic constraint (gnomAD): Loss-of-function variants: 2 observed, 6.46 expected, observed/expected ratio (o/e) 0.31, 90% interval 0.13 to 0.97. That is too few expected variants to judge how well the gene tolerates losing a copy. Missense variants: 54 observed, 65.83 expected, observed/expected ratio (o/e) 0.82, 90% interval 0.66 to 1.03. Synonymous variants: 25 observed, 26.04 expected, observed/expected ratio (o/e) 0.96, 90% interval 0.7 to 1.34.